STAT4 (signal transducer and activator of transcription 4)
Diseases named in the same sentence as STAT4 in open-access papers (continued):
Sharing a sentence is not in itself a finding about the gene and the disease.
chronic obstructive pulmonary disease (2 papers, 2019 to 2022). A chronic and progressive lung disorder characterized by the loss of elasticity of the bronchial tree and the air sacs, destruction of the air sacs wall, thickening of the bronchial wall, and mucous accumulation in the bronchial tree. "Liuweibuqi capsules were reported to be effective in treating chronic obstructive pulmonary disease (COPD) through antagonizing STAT4, but activating STAT6." (PMID 36324680, 2022).
co-infection (2 papers, 2024 to 2025). "Nonetheless, persistent STAT3 activation and further upregulation of STAT4 — a key regulator of Th1 differentiation — could exacerbate chronic inflammation and tissue damage in co-infection." (PMID 41394852, 2025). "Therefore, we analyzed the differential expression of STAT family genes and found that HIV-mono infection leads to the upregulation of STAT3 and STAT4, whereas co-infection results in the upregulation of STAT1 and STAT2." (PMID 41394852, 2025). "Distinctly, VL1 patient, that has disorganized spleen and VL-HIV coinfection was related to SOD1, STAT3, STAT4, ICOS, TRAF6 and IRF3 genes, and CD8+ cells in the RP and expression of IL6 in both regions of spleen." (PMID 38843306, 2024).
coccidioidomycosis (2 papers, 2021 to 2024). A fungal infection caused by Coccidioides immitis. "One variant found in a family with three generations of disseminated coccidioidomycosis was a missense mutation in STAT4." (PMID 38535182, 2024). "In the case of the Stat4 mutation from a family with 3 generations of disseminated coccidioidomycosis, the vaccinated mice showed no dissemination and appeared as protected as normal mice in this short term study." (PMID 35071044, 2021).
dermatomyositis (2 papers, 2014 to 2024). Dermatomyositis (DM) is a type of idiopathic inflammatory myopathy characterized by evocative skin lesions and symmetrical proximal muscle weakness. "Moreover, we have recently shown that a polymorphism (rs7574865) in the signal transducer and activator of transcription 4 gene (STAT4) is associated with adult-onset polymyositis and dermatomyositis in a Japanese population." (PMID 24632671, 2014). "Therefore, additive effects of C8orf13–BLK and STAT4 were observed, most notably in dermatomyositis." (PMID 24632671, 2014).
endothelial dysfunction (2 papers, 2021 to 2023). In vascular diseases, endothelial dysfunction is a systemic pathological state of the endothelium (the inner lining of blood vessels) and can be broadly defined as an imbalance between vasodilating and vasoconstricting substances produced by (or acting on) the endothelium. "In conclusion, Cbl alleviates endothelial dysfunction by inactivation of the JAK2/STAT4 pathway and inhibition of Runx3 expression in DM." (PMID 34798872, 2021). "Herein, we aimed to determine whether E3 ubiquitin ligase casitas B-lineage lymphoma (Cbl) alleviates endothelial dysfunction in DM rats by JAK2/STAT4 pathway." (PMID 34798872, 2021). "In conclusion, this study elucidates the mechanism that Cbl alleviates endothelial dysfunction in DM through inhibiting the JAK2/STAT4 pathway and Runx3 expression, providing novel insight into targeted therapy against DM and comprehensive understanding on DM progression." (PMID 34798872, 2021). "In a word, downregulation of JAK2 and STAT4 might alleviate endothelial dysfunction in DM rats." (PMID 34798872, 2021).
fibrosis (2 papers, 2015 to 2018). the formation of excess fibrous connective tissue in an organ or tissue in a reparative or reactive process. "Similarly, in our studies, we have shown that IL-6 and IL-10 were increased in patients with fibrosis, together with STAT4 and STAT6." (PMID 30205811, 2018).
gout (2 papers, 2015 to 2025). A condition characterized by painful swelling of the joints, which is caused by deposition of urate crystals. "We therefore propose IL-33, IL-1RL1, IL-23R, and STAT4 as potential candidate susceptibility genes for gout." (PMID 26399911, 2015). "The current study therefore aimed to investigate the associations between the IL-33 rs3939286 A/G, IL-1RL1 rs13015714 G/T, IL-23R rs10889677 A/C, and STAT4 rs7574865 G/T single nucleotide polymorphisms (SNPs) and the risk of gout." (PMID 26399911, 2015). "The aim of this study was to investigate the associations between genetic variants in the interleukin (IL) and interleukin receptor (ILR) genes IL-33, IL-1RL1, IL-23R, and signal transducer and activator of transcription 4 (STAT4) and susceptibility to gout in Chinese Han male individuals." (PMID 26399911, 2015). "The STAT family (STAT1/STAT3/STAT4) mediates cytokine signaling in gout pathogenesis." (PMID 40613560, 2025). "The genetic distributions of rs3939286 in IL-33, rs13015714 in IL-1RL1, rs10889677 in IL-23R, and rs7574865 in STAT4 were detected in 1100 men with gout and 1227 ethnically matched controls, using Taqman allelic discrimination real-time polymerase chain reaction (PCR)." (PMID 26399911, 2015). "The production and function of cytokines may be affected by polymorphisms in the functional regions of their genes, suggesting that IL-33, IL-1RL1, IL-23R, and STAT4 may be candidate genes for the inflammatory pathogenesis of gout." (PMID 26399911, 2015). "STAT1 and STAT4 may also contribute to immune cell activation in gout pathology." (PMID 40613560, 2025).
Hepatitis (2 papers, 2013 to 2020). Inflammation of the liver. "It has been shown, STAT4 deficient mice exhibited an increased susceptibility to ConA in ConA-induced hepatitis." (PMID 31899535, 2020). "STAT4 is important for IL-22 production, which plays a pathological role in IL-17-dependent hepatitis." (PMID 23990947, 2013).
lupus erythematosus (2 papers, 2019 to 2023). An autoimmune, connective tissue chronic inflammatory disorder affecting the skin, joints, kidneys, lungs, heart, and the peripheral blood cells. "In patients with lupus erythematosus (SLE), a STAT4 SLE disease risk variant has been associated with increased sensitivity of IL-12-induced activity of the STAT4 signaling pathway in primed T cells." (PMID 30917537, 2019).
malaria (2 papers, 2013 to 2018). Malaria is a serious and sometimes fatal disease caused by a parasite that commonly infects a certain type of mosquito which feeds on humans. "This lack of confounding by acquired risk factors for NTS is in keeping with the absence of observed association between genetic variation at the STAT4 locus or HIV and malaria-related phenotypes in GWAS published to date." (PMID 29523850, 2018). "As carriage of HbSS is associated with risk of NTS bacteraemia, and carriage of HbAS is associated with a key risk factor for NTS bacteraemia (malaria), we sought to assess whether the observed association at the STAT4 locus is independent of genotype at rs334." (PMID 29523850, 2018).
neuromyelitis optica (2 papers, 2018 to 2024). A rare inflammatory disease of the central nervous system characterized mainly by attacks of uni- or bilateral optic neuritis (ON) and acute myelitis. "Furthermore, studies of different populations indicated that rs11889341/rs10181656 in STAT4 were associated with dilated cardiomyopathy and neuromyelitis optica spectrum disorders." (PMID 30054428, 2018).
oral lichen planus (2 papers, 2020 to 2022). Oral lichen planus is a chronic inflammatory oral condition of unknown aetiology characterized by T-cell-mediated chronic immune response and abnormal epithelial keratinization cycle. "The aim of this study was to evaluate the expression of proteins: JAK3, STAT2, STAT4 and STAT6 in epithelium lesions in patients with pemphigus vulgaris (PV), bullous pemphigoid (BP), oral lichen planus (LP) and chronic ulcerative stomatitis (CUS), as well as in the control group." (PMID 36613766, 2022).
pemphigus vulgaris (2 papers, 2020 to 2022). Pemphigus is a group of chronic autoimmune skin diseases characterized by blister formations on the outer layer of the skin and the mucous membranes. "That is why the aim of this study was to evaluate the expression of proteins JAK3, STAT2, STAT4, and STAT6 in skin lesions and perilesional area in patients with pemphigus vulgaris as well as in the control group." (PMID 32170648, 2020).
preeclampsia (2 papers, 2020 to 2024). Preeclampsia is a hypertensive disorder of pregnancy that is characterized by new-onset hypertension with proteinuria presenting after 20 weeks of gestation, and depending on mild or severe forms may initially present with severe headache, visual disturbances, and hyperreflexia. "The serum levels of STAT4 and sEng were significantly increased in preeclampsia with disease severity status, which have promise as diagnostic markers in preeclampsia." (PMID 31628681, 2020). "Correlation between STAT4 and sEng, and their diagnostic value in preeclampsia were analyzed." (PMID 31628681, 2020). "The expression of STAT4 and sEng in peripheral blood of patients with mild preeclampsia was positively correlated (r = .808, P < .001)." (PMID 31628681, 2020). "For the diagnosis of preeclampsia by the serum STAT4, AUC is 0.902, and the sensitivity and specificity are 0.893 and 0.929." (PMID 31628681, 2020). "This study analyzed the expression of STAT and sEng in the preeclampsia and normal pregnancy patients, and the relationship between STAT4 and sEng in preeclampsia." (PMID 31628681, 2020). "The circulating levels of STAT4 were 0.340 ± 0.062, 0.637 ± 0.159, and 1.513 ± 0.182 ng/mL in the control group, mild preeclampsia group, and severe preeclampsia group, with statistically significant difference (P < .01)." (PMID 31628681, 2020). "The expression of STAT4 and sEng in peripheral blood of severe preeclampsia was also positively correlated (r = .807, P < .001)." (PMID 31628681, 2020). "For the diagnosis of preeclampsia by the serum STAT4, AUC is 0.902, and the sensitivity and specificity are 0.893 and 0.929, respectively." (PMID 31628681, 2020). "The limitation of this study is the levels of sEng and STAT4 in cases that were diagnosis with preeclampsia versus normal pregnant women." (PMID 31628681, 2020). "In this study, we detected the expression of STAT4 and sEng in the serum of patients with preeclampsia and found increase in STAT4 levels in preeclampsia, which were closely related to the condition of the disease." (PMID 31628681, 2020). "In conclusion, both STAT4 and sEng have diagnosis values for preeclampsia, but the sensitivity and specificity of STAT4 were better than sEng, suggesting STAT4 can be used as a novel serum marker for diagnosis of preeclampsia, and thus postponed the development of the disease." (PMID 31628681, 2020). "The circulating levels of STAT4 and sEng were significantly increased in the preeclampsia." (PMID 31628681, 2020). "The more severe the preeclampsia, the higher the STAT4 level." (PMID 31628681, 2020). "The serum levels of STAT4 and sEng in preeclampsia were positively correlated." (PMID 31628681, 2020). "Here, we reported that STAT4 and sEng involved in preeclampsia." (PMID 31628681, 2020).
primary immunodeficiencies (2 papers, 2021 to 2025). "One vaccine challenge study was performed for each of the following strains of mice with a primary immunodeficiency: Stat4 KO, Ifngr KO, mut-Stat3, Dectin-1 KO, Rag-1 KO." (PMID 35071044, 2021). "Evaluation for primary immunodeficiencies in our patient revealed mutations in IL-12-RB1 and STAT4." (PMID 41235083, 2025).
renal fibrosis (2 papers, 2023 to 2026). A final common manifestation of a wide variety of chronic kidney diseases characterized by glomerulosclerosis and tubulointerstitial fibrosis. "Since renal fibrosis is characterized by activation of inflammatory responses, STAT4 signaling pathway may also be involved in renal fibrosis." (PMID 37194066, 2023).
rosacea (2 papers, 2021 to 2025). A chronic erythematous skin disorder that affects the face. "Based on the ol-DEGs, we revealed the TF regulatory network in AD/rosacea, indicating a central role of the 24 TFs in regulating the pathogenesis of AD and rosacea, including PPARG, STAT4, sox9, and RORA." (PMID 34899707, 2021). "STAT4 is an essential mediator of inflammation by regulating IFN-γ, which is closely related to the progression of AD and rosacea." (PMID 34899707, 2021). "In rosacea, proteomic and transcriptomic investigations have revealed enrichment of neurodegeneration-related proteins such as SNCA, GSK3B, and HSPA8, as well as regulatory hubs including PPARG, STAT4, and RORA, which converge on NF-κB, IL-17, and TNF signaling pathways." (PMID 41465136, 2025).
sarcoidosis (2 papers, 2012 to 2013). Sarcoidosis is a multisystemic disorder of unknown cause characterized by the formation of immune granulomas in involved organs. "Of the 31 TCR/JS/CCR-gene signature genes, 8/31 genes were cited in the sarcoidosis literature with CD28, IFNG, IL7R, AKT3, IL2RA, IL2RB, and STAT4 demonstrating a robust relationship with these terms." (PMID 22984568, 2012).
scleroderma (2 papers, 2020 to 2023). Scleroderma is a rare autoimmune connective tissue disorder characterized by abnormal hardening of the skin and, sometimes, other organs. "Our scleroderma skin grafts to humanized mice support IL-6 trans-signaling as a key driver of skin fibrosis in pansclerotic morphea and align our results with recent identification of STAT4 mutations driving IL-6 expression in the childhood form of pansclerotic morphea." (PMID 37669366, 2023).
triple-negative breast carcinoma (2 papers, 2023 to 2025). An invasive breast carcinoma which is negative for expression of estrogen receptor (ER), progesterone receptor (PR), and human epidermal growth factor receptor 2 (HER2). "In this study, expression of the E7 oncogene in triple-negative breast cancer cells led to a decrease in the expression of the STAT4, JAK2, and STAT3 genes, which are key mediators of the immune response." (PMID 40733498, 2025). "In our study, we observed that HPV16 E7 expression in triple-negative breast cancer cells led to a significant reduction in the expression of JAK2 and STAT4, central components of cytokine-mediated immune response pathways." (PMID 40733498, 2025). "Additionally, in triple negative breast cancer (z score = 2.68, p = 0.00731), a lower CTL level indicated a better survival outcome when STAT4 were high expressed." (PMID 36968603, 2023).
tuberculosis (2 papers, 2011 to 2018). A chronic, recurrent infection caused by the bacterium Mycobacterium tuberculosis. "In animal models of tuberculosis, the transcription factor STAT4, which is involved in Th1 development, is critical for mounting an effective Th1 immune response and clearance of M.tuberculosis from the lungs." (PMID 21829471, 2011).
AIDS (1 paper, 2025). A syndrome resulting from the acquired deficiency of cellular immunity caused by the human immunodeficiency virus (HIV). "Several top-ranking genes, including BLK, STAT4, and TNIP1, have been previously implicated in SjD and other AIDs, validating our approach." (PMID 40429780, 2025).
alopecia areata (1 paper, 2024). Loss of scalp and body hair involving microscopically inflammatory patchy areas. "STAT4 gene expression was significantly correlated with alopecia areata." (PMID 39728991, 2024).
anaplastic large cell lymphoma (1 paper, 2023). Anaplastic large cell lymphoma (ALCL) is a rare and aggressive peripheral T-cell non-Hodgkin lymphoma, belonging to the group of CD30-positive lymphoproliferative disorders, which affects lymph nodes and extranodal sites. "There was a mild STAT4 downregulation in angioimmunoblastic T-cell lymphoma (AITL), anaplastic large-cell lymphoma (ALCL), and peripheral T-cell lymphoma, which was not otherwise specified (PTCL-NOS)." (PMID 37173993, 2023).
anterior uveitis (1 paper, 2013). Inflammation of the iris and anterior chamber of the eye. "Likewise, based on the statistical power of our study, an effect of the STAT4 rs897200 and rs7574070 genetic variants similar to that described for BD could be discarded in non-anterior uveitis." (PMID 24312163, 2013). "In conclusion, our data do not support a relevant role of IL23R and STAT4 polymorphisms in the genetic susceptibility to develop non-anterior uveitis." (PMID 24312163, 2013).
babesiosis (1 paper, 2023). Babesiosis refers to a condition caused by microscopic parasites that infect the red blood cells. "However, an important inhibitor of IL-12 mediated STAT4 activation is SOCS363 which was found to be expressed significantly higher in dogs with advanced babesiosis (Babesia 2 group)." (PMID 36739305, 2023). "However, the expression of STAT4 gene was generally similar in dogs with mild/moderate babesiosis (Babesia 1), infected with D. repens and co-infected with B. canis and D. repens (Bab + Diro) and differences in expression between groups were not statistically significant." (PMID 36739305, 2023). "The higher expression of STAT4 and IFN-γ is consistent with the hypothesis that in Babesia infections the immune response is skewed towards a Th1-profile." (PMID 36739305, 2023). "Activation of STAT4, involved in controlling Th1 gene expression, induces production of IFN-γ62 and as we had predicted the highest expression of IFN-γ was indeed observed in dogs with advanced babesiosis (Babesia 2)." (PMID 36739305, 2023).
blepharitis (1 paper, 2010). Inflammation of the eyelids near the eyelashes. "Mock-vaccinated STAT4−/− and BALB/c mice exhibited similar levels of blepharitis, and both groups had significantly higher levels of blepharitis than did their vaccinated counterparts (p<0.0001)." (PMID 20104254, 2010). "Vaccinated STAT4−/− and BALB/c mice were completely protected against blepharitis (KOS, p>0.05)." (PMID 20104254, 2010). "Thus, the absence of STAT4 did not alter the level of blepharitis or CS in either vaccinated or mock-vaccinated mice." (PMID 20104254, 2010).
cardiomyopathy (1 paper, 2017). A disease of the heart muscle or myocardium proper. "Analysis of pathways that were dysregulated across cardiomyopathy phenotypes identified shared genes that were associated with extracellular matrix remodeling and thus likely fibrosis (THY1, CILP, OGN, THBS4, ASPN, HAPLN1,and SMOC2), as well as calcium (ADIPOQ, ASPN, THBS4, STAT4, and SMOC2)." (PMID 28098235, 2017).
Cervical lymphadenopathy (1 paper, 2019). Enlarged lymph nodes in the neck. "However, a significant portion of Stat4−/− mice showed prominent cervical lymphadenopathy and metastatic nodules on their lungs, both of which were mostly absent in WT mice." (PMID 32010142, 2019).
cervical tumor (1 paper, 2020). "Together, these data indicate a possible relationship between STAT4, progression, and metastasis in cervical tumor cells, as well as the role of oncoproteins such as E7 on the expression of STAT4." (PMID 33076315, 2020).
chronic mucocutaneous candidiasis (1 paper, 2020). "For instance, inherited genetic mutations in the Th17 pathway (e.g., STAT1, STAT3, STAT4) are known to lead to several diseases such as chronic mucocutaneous candidiasis (CMC), Hyper-IgE syndrome (HIES) and autoimmune polyendocrinopathy–candidiasis–ectodermal dystrophy (APECED)." (PMID 31972980, 2020).
cryptococcosis (1 paper, 2024). An acute or chronic, localized or disseminated infection by Cryptococcus neoformans. "The authors first used single-cell RNA sequencing to identify that Batf3-dependent cDC1 exhibited a unique mRNA signature during murine cryptococcosis, strongly upregulating transcripts related to T cell recruitment and Th1 polarization, such as Il12b, Stat4, and Ccl22." (PMID 39254303, 2024).
cysticercosis (1 paper, 2011). "Conversely, Th1 response induced via STAT4-dependent signaling pathway is essential for development of immunity against cysticercosis." (PMID 22206032, 2011).